RN7SL22P (RNA, 7SL, cytoplasmic 22, pseudogene)
Gene: Miscellaneous RNA gene on chromosome 9 (35,671,776 to 35,672,044, forward strand). Ensembl gene ENSG00000243136.
Homologues: Orthologues: chimpanzee Metazoa_SRP (99% identical), macaque Metazoa_SRP (94% identical). Paralogues in human: RN7SL1 (84% identical), RN7SL2 (83% identical), RN7SL45P (83% identical), RN7SL126P (83% identical), RN7SL3 (82% identical), RN7SL625P (81% identical), RN7SL664P (81% identical), RN7SL431P (80% identical), RN7SL786P (80% identical), RN7SL177P (80% identical), RN7SL186P (80% identical), RN7SL43P (80% identical), and 701 more.